CEP55 (centrosomal protein 55)
Diseases named in the same sentence as CEP55 in open-access papers (continued):
Sharing a sentence is not in itself a finding about the gene and the disease.
tumor (continued). "The bioinformatics databases from Oncomine and TCGA summarized that CEP55 amplification is more frequently found in a wide range of tumor types than deep deletion events." (PMID 35517890, 2022). "Knockdown of SNHG12 blocked E2F1 recruitment and down-regulated the expression of CEP55, thereby inhibiting tumor formation and angiogenesis in nude mice." (PMID 35597996, 2022). "Compared with silencing E2F1 alone, simultaneous silencing E2F1 and overexpressing CEP55 enhanced tumor growth." (PMID 35597996, 2022). "CEP55 is a major player in cytokinesis, participates in PI3K/AKT signaling pathway, and is associated with tumor progression." (PMID 35814389, 2022). "In the four data sets of TCGA colorectal, Gaedcke colorectal, Skrzypczak colorectal, and Hong colorectal, we found that CEP55 expression was higher in tumor tissues than in healthy tissues." (PMID 33190424, 2021). "The OR was 12.25 (95%CI: 1.27–118.36) for tumor differentiation, and 5.50 (95%CI: 1.15–26.41) for metastasis in high CEP55 expression." (PMID 34650590, 2021). "The level of CEP55 mRNA in the tumor tissues was significantly higher compared with that in the corresponding nontumor tissues by quantitative analysis." (PMID 34104194, 2021). "Subsequent validation in the GEPIA2 database found the same results, with CEP55 having higher expression in tumor tissues, such as CRC." (PMID 33190424, 2021). "TOP2A and CEP55 interacted significantly within the network, and based on the data from GEPIA, TOP2A was more upregulated than CEP55 in tumor samples." (PMID 34787052, 2021). "As previously documented, CEP55 showed abundant expression and played a tumor-promoting role in RCC." (PMID 37305161, 2021). "To further decipher the impact of overexpressed Cep55 on tumorigenesis, we established cell lines from some of the tumors that developed in Cep55 overexpressing mice (herein abbreviated as tumor cell lines (TCLs)), in particular haemangiosarcoma of the liver." (PMID 33087841, 2020). "The knockdown of CEP55 can significantly inhibit the viability and proliferation of a tumor cell and even lead to tumor cell death." (PMID 32337246, 2020). "Taken together, our data suggest that hyperstabilised microtubules and defective cytokinesis in Cep55-overexpressing cells might be major source of chromosome segregation errors and tetraploidization that can predispose these cells to GI which over time might facilitate tumor development." (PMID 33087841, 2020). "circ_001287 can up-regulate CEP55 by binding to miR-144, which resulted in increased proliferative, invasive and migratory capacities and tumor growth in vivo." (PMID 33256799, 2020). "CEP55 is expressed in normal tissues and tumor cells, and is coupled with centrosomes and intermediates in the cell cycle, and plays a role in regulating cell cycle after phosphorylation." (PMID 31422942, 2019). "The investigation of the biological function of SPAG5 in HCC demonstrated that SPAG5 exerted oncogenic activities to promote tumor growth and metastasis via interaction with CEP55." (PMID 30089483, 2018). "In contrast, MMP2, MMP9, and Cyclin D1 levels were decreased in tumour tissues with downregulated CEP55 expression." (PMID 28724890, 2017). "Conversely, CEP55-silenced cells presented much slower tumour growth rates and formed smaller tumours." (PMID 28724890, 2017). "Quantitative immunohistochemical analysis revealed that the H-score of CEP55 staining was significantly increased in PANC specimens compared with that in adjacent non-tumour tissues (P < 0.05)." (PMID 28724890, 2017).
tumor (continued). "Critically, through clustered regularly interspaced short palindromic repeats screening, we identified Centrosomal Protein 55 (CEP55) as a key molecule modulating tumor immune evasion, mechanistically confirming its role in regulating T cell‐mediated antitumor immune responses." (PMID 40236779, 2025). "Moreover, CEP55 knockdown effectively inhibited the growth of xenograft tumors derived from Bel-7402 and Hep-3B cells, with tumor volumes in the shCEP55 group being significantly smaller than those in the control group." (PMID 40771801, 2025). "Therefore, the finding that CEP55 promotes tumour survival and growth by being overexpressed in numerous malignancies is not unexpected." (PMID 39911278, 2025). "Moreover, in xenograft models, CEP55 knockdown significantly reduced tumor growth and proliferation, as evidenced by decreased tumor volume, lower CEP55 and Ki-67 expression." (PMID 40771801, 2025). "Various studies have confirmed that the high expression of CEP55 is often accompanied by the synergistic activation of other oncogenes, suggesting that it may jointly drive tumor progression through multi-molecular networks." (PMID 40918457, 2025). "In vitro and vivo experiments were conducted to assess the role of CEP55 in tumor progression." (PMID 40771801, 2025). "By addressing tumor cell proliferation and immune evasion mechanisms, CEP55‐targeted strategies could potentially overcome existing limitations in immunotherapy and improve patient outcomes." (PMID 40236779, 2025). "Additionally, elevated CEP55 expression in diverse tumor types underscores its involvement in tumorigenesis, highlighting its potential as a tumor-promoting factor." (PMID 40918457, 2025). "Considering the role of CEP55 in AM, further investigations could explore its function in other tumor types to assess its potential as a target gene across a broader range of malignancies, thus expanding the clinical relevance of this study." (PMID 40918457, 2025). "However, the precise roles of ILF3 and CEP55 in regulating tumor cell ferroptosis in vivo warrants further investigation." (PMID 39871389, 2025). "Moreover, in xenograft models, CEP55 knockdown significantly reduced tumor growth and proliferation." (PMID 40771801, 2025). "Besides, CEP55 participates in the remodeling of the tumor immune microenvironment and regulates the process of tumor immune response." (PMID 40918457, 2025). "Consistent with the results, knocking down CEP55 reduced Treg infiltration in tumor tissues." (PMID 38250876, 2024). "Additionally, the levels of the proliferation marker Ki67 and CEP55 in tumor tissues were markedly decreased by LINC01087 knockdown." (PMID 39023191, 2024). "To investigate whether the knockout of CEP55 affects tumor development in vivo, we knocked out the expression of CEP55 in CT26 and MC38 cell lines using CRISPR-Cas9 genomic editing technology." (PMID 38250876, 2024). "Notably, knocking out CEP55 significantly slowed tumor growth compared to wild-type (WT) and vector control cells in animal models." (PMID 38250876, 2024). "Treatment with anti-PD1 significantly reduced tumor growth in CEP55 knockout tumors compared to control tumors, suggesting that inhibiting CEP55 could improve the efficacy of ICIs." (PMID 38250876, 2024). "Here, we examined the role of CEP55 in shaping the tumor immune microenvironment in CRC." (PMID 38250876, 2024). "Notably, the wild-type tumor treated with anti-PD1 had a tumor size like that of the CEP55 KO tumor treated with isotype." (PMID 38250876, 2024). "These profiles show that CEP55 expression is selectively correlated with the infiltration of immune cell populations into tumors and may serve as a key regulator in the tumor microenvironment." (PMID 37484531, 2023).
tumor (continued). "The results of immunohistochemistry analysis showed that CEP55 was moderately expressed in tumor tissue, with a lower expression level in normal tissue, while SMS exhibited low expression in tumor tissue and could not be detected in normal tissue." (PMID 38097948, 2023). "Moreover, CEP55 expression was positively correlated with immune cell infiltration, immune checkpoints, and immune-related genes in the tumor microenvironment." (PMID 37887301, 2023). "Collectively, these findings suggest that CEP55 may antagonize or promote tumor initiation and progression by mediating immune infiltration involved in tumor immune regulation." (PMID 37887301, 2023). "The possible involvement of CEP55 in the tumor microenvironment warrants further investigation." (PMID 37484531, 2023). "CEP55 immunohistochemistry (IHC) staining was weaker in normal breast, glial, oral (head and neck), lung, ovary, pancreas, kidney, and endothelial tissues (endometrium) and higher in tumor tissues." (PMID 37887301, 2023). "Importantly, the cytoplasmic stabilization of CEP55 by α‐catenin is just one possibility of how CEP55 expression is regulated in tumor cells." (PMID 37381005, 2023). "Additionally, it was also discovered that CEP55 is expressed in regulatory T-cells (Tregs) and tumor cells (F)." (PMID 37980163, 2023). "Additionally, CBX2 and CEP55 had a significantly greater impact on tumor patient survival than PDCD1 and CD274." (PMID 37980163, 2023). "Three scRNA-seq datasets GSE125449, GSE140228 and GSE166635 downloaded from the TISCH2 database were analyzed, and we found that CBX2 was primarily expressed in cancerous tumor cells while CEP55 was primarily expressed in T cells that were proliferating (T prolif), whose marker gene MKI67." (PMID 37980163, 2023). "Along with an increase in CBX2 and CEP55, the stepwise stage and tumor grade also increased." (PMID 37980163, 2023). "In summary, the critical role of CEP55 in immune infiltration and ICPs may make it a promising target for tumor immunotherapy." (PMID 37887301, 2023). "Moreover, we elaborated on the multi-omics features of CEP55 and its role in tumor immunity and screened latent target compounds." (PMID 37887301, 2023). "Moreover, we evaluated the expression level of CEP55 according to the age of patients in each tumor type." (PMID 37887301, 2023). "CEP55 is a powerful tumor prognostic marker that is involved in tumor immune modulation." (PMID 37484531, 2023). "The proportions of poorly differentiated tumor and distant metastasis were significantly higher in the high CEP55 group (p = 0.031, p = 0.028), whereas the proportions of old age, male gender, tumor location, tumor size and clinical stage were not significantly different between these two groups." (PMID 34650590, 2021). "Moreover, the expression of CEP55 protein was also higher in tumor tissues than in adjacent normal tissues." (PMID 34104194, 2021). "Likewise, constitutive Cep55 knockdown in this line using shRNAs reduced anchorage-independent colony formation, G2/M cell population along with reduced proliferation capacity and tumor formation dependent on the extent of reduction of Cep55 levels." (PMID 33087841, 2020). "The higher the expression of CEP55 was, the poorer the differentiation of tumor cells." (PMID 32337246, 2020). "We monitored a cohort of wild type (herein referred to as Cep55wt/wt, n = 40), heterozygous transgenic (Cep55wt/Tg, n = 40), and homozygous transgenic (Cep55Tg/Tg, n = 50) Cep55 mice (both males and females) over a period of 2.5 years for spontaneous tumor formation." (PMID 33087841, 2020). "Notably, partial depletion of Cep55 (50%) in TCLs significantly delayed tumor initiation and progression, while near-complete depletion (90%) totally impaired tumor initiation in a xenograft model." (PMID 33087841, 2020). "The knockdown of CEP55 was found to inhibit tumor cell viability and proliferation." (PMID 32337246, 2020).
tumor (continued). "Engrafting a partial CEP55‐knockdown MDA‐MB‐231 derivative (sh#2) showed a significant reduction in tumor growth while a near‐complete CEP55 reduction (sh#8) abrogates tumor formation in NOD/SCID mice (3 mice/group are shown as an example), suggesting that CEP55 is essential for tumor formation." (PMID 30108112, 2018). "Taken together, our findings indicate that elevated expression of CEP55 is correlated with tumor invasiveness and may be an independent prognostic factor for clinical outcomes in human HCC patients." (PMID 30096813, 2018). "Importantly, the expression of CEP55 increased gradually along with progression of HCC from tumor-node-metastasis (TNM) stages I to IV." (PMID 30096813, 2018). "In addition, the expression of CEP55 was shown to be significantly elevated in HCC tumor tissues of deceased patients compared with the HCC tissues of living patients." (PMID 30096813, 2018). "Immunoblot analysis of tumor lysates showed reduced CEP55 and enhanced cleaved caspase‐3." (PMID 30108112, 2018). "Current studies have shown that CEP55 promotes tumor progression via PI3K/AKT/mTOR pathway." (PMID 30089483, 2018). "Importantly, the enhanced tumourigenicity was reversed by IκBα and the tumour volume was much smaller compared with that in CEP55-overexpressing Capan-1 cells." (PMID 28724890, 2017). "Western blotting and immunohistochemical assays revealed the upregulation of invasion-related proteins MMP2 and MMP9, and proliferation-related protein Cyclin D1 in the CEP55-overexpressing tumour tissues, which coincided with the aggressive phenotype displayed by Capan-1/CEP55 cells." (PMID 28724890, 2017). "However, further studies on the relationship between CEP55 expression and the tumor microenvironment are still needed to determine whether CEP55 can be used as a biomarker to predict OSCC immunotherapy response." (PMID 40386043, 2025). "However, in our study, knocking down CEP55 inhibited the progression of PAAD, so CEP55’s tumor-promoting effect may outweigh its effect of enhancing cuproptosis to inhibit PAAD." (PMID 40677006, 2025). "Moreover, WB confirmed elevated CEP55 expression in tumor tissues." (PMID 40918457, 2025). "We next asked whether deleting CEP55 can change the tumor’s response to ICIs." (PMID 38250876, 2024). "Furthermore, we investigated whether knocking out CEP55 could enhance T cell infiltration in the tumor, thus improving the efficacy of ICI." (PMID 38250876, 2024). "Therefore, increasing the methylation level of CEP55 is also a new way to target tumor therapy." (PMID 37887301, 2023). "Thus, these clinically available compounds could bind CEP55, and further studies should be conducted to evaluate the outcomes of CEP55 inhibition in a tumor context." (PMID 37484531, 2023). "Finally, using a connectivity map (CMap) and molecular docking analyses, we identified three potential small molecules targeting CEP55, which may mitigate the immunosuppressive microenvironment and enhance the anti-tumor effect of ICIs." (PMID 37484531, 2023). "However, alternative approaches targeting upstream regulatory mechanisms of CEP55 may also present possible strategies to block its tumor-supporting properties." (PMID 37381005, 2023). "The expressions of CEP55 and Ki67 were detected by immunohistochemistry and Western blot analysis, the results of which revealed down‐regulated expressions of CEP55 and Ki67 in tumour tissues of nude mice bearing SiHa cells co‐cultured with miR‐144‐3p‐treated EVs." (PMID 33417281, 2021). "Moreover, CEP55 was shown to be predominantly located in the cytoplasm of tumor cells." (PMID 26615423, 2016). "However, the relationship between CEP55 and tumor immune infiltration in OSCC remains unclear." (PMID 40386043, 2025). "Using tumor samples from our cohort of 29 patients and an RT-qPCR approach, we found that FBXO39 and CEP55 genes were highly expressed in GBM and that their expression predicted the OS (P < 0.05)." (PMID 40504854, 2025).
tumor (continued). "Kaplan–Meier (K–M) survival analysis indicated that CEP55 knockdown, especially in combination with anti‐programmed cell death protein 1 (anti‐PD1) therapy, significantly improved survival rates in tumor‐bearing mice (p < 0.05)." (PMID 40236779, 2025). "In order to investigate the effect of CEP55 on tumor growth in vivo, xenograft models were established in BALB/c nude mice using Bel-7402 and Hep-3B HCC cell lines with CEP55 knockdown." (PMID 40771801, 2025). "Furthermore, in mice with the Tsn-deficient version, adoptive transfer of the cep55-specific CTL line could not stop tumor development." (PMID 40098955, 2025). "The main findings are that CEP55 interacts with the p85 regulatory subunit of PI3KCA and thereby stimulates the PI3K-Akt pathway and cellular proliferation in different tumor types." (PMID 39195269, 2024). "This is important because the knockout CEP55 and anti-PD1 combination significantly reduces tumor size." (PMID 38250876, 2024). "In conclusion, our study unveils a potential immunoregulatory role of CEP55 in CRC, illuminating its influence on the tumor microenvironment and therapeutic response to ICIs." (PMID 38250876, 2024). "Among the 991 BC tumor samples, GATA3 had the highest frequency of somatic SNVs, accounting for 13%; followed by FOXA1, accounting for 3%; AGR2, CA12, CEP55, CDC20, TBC1D9, and MELK had very few somatic SNVs." (PMID 39440050, 2024). "These genes formed a highly interconnected network, with key central nodes such as AURKB, CEP55, CCNB2, and MCM10, suggesting their involvement in common pathways potentially driving aggressive tumor behavior and contributing to poor patient prognosis." (PMID 39596419, 2024). "Moving to the tumor stage, ACC, KIRC, KIRP, LIHC, LUAD, UCEC, and LUSC (p < 0.001) showed a positive correlation between CEP55 expression and tumor stage." (PMID 37175004, 2023). "Collectively, these results demonstrated the notion that CEP55 augments the proliferation of GBC cells in vitro and promotes the growth of GBC in tumor xenograft models of GBC." (PMID 37274251, 2023). "Core genes (CEACAM1, CEP55, MELK) and were found to be involved in tumor, inflammation, necrosis, and proliferation." (PMID 37589542, 2023). "As CEP55 is also transcriptionally regulated by the YAP/TEAD/FoxM1 complex, several molecular mechanisms cooperate in CEP55-dependent tumor cell dissemination." (PMID 37381005, 2023). "In TCGA cohort, CEP55 expression was correlated with age, serum AFP level, pathologic stage, histologic grade, and tumor recurrence (p < 0.05)." (PMID 37484531, 2023). "It is worth mentioning that only one tumor, namely, LAML, experienced the opposite pattern where CEP55 expression was significantly higher in normal tissue versus cancerous one." (PMID 37175004, 2023). "The DEGs and hub genes screened and identified in this study will help us to understand the molecular mechanisms of NSCLC, and CEP55 expression affects the survival and prognosis of patients with NSCLC, and participates in tumor immune response." (PMID 36404510, 2022). "Seven pairs of tumor and adjacent non-tumorous tissues were selected to verify the expressions of the ZWINT, RRM2, NDC80, KIF4A, CEP55, CENPU, and CENPF genes." (PMID 35028418, 2022). "We extracted the CEP55 transcriptional information of CRC samples from the TCGA database and found that CEP55 was significantly highly expressed in CRC tumor tissues by t test." (PMID 33190424, 2021). "In tumor samples, most of the HCC samples had medium (5/7) CEP55 staining, and most of the CCA samples similarly had medium (3/5) CEP55 staining." (PMID 32337246, 2020). "The up-regulated CEP55, IFI44, NCF4, and TCIRG1 with HR > 1 were regarded as oncogenes and were proved to be closely related to tumor progression by using comprehensive bioinformatics analysis." (PMID 33101364, 2020).